CD34 (CD34 molecule)
Diseases named in the same sentence as CD34 in open-access papers (continued):
Sharing a sentence is not in itself a finding about the gene and the disease.
acute GVHD (12 papers, 2015 to 2025). "The present study revealed possible involvement of the HPSE gene insulator in susceptibility to CMV infection and showed that CMV serostatus alters previously found correlations with the risk of acute GVHD and the yield of CD34+ cell mobilization." (PMID 34943994, 2021). "We have demonstrated that high CD3+ (>347 × 10^6/kg) and CD34+ (>8.25 × 10^6 /kg) cell dose content in the grafts is an independent prognostic factor associated with higher probability of severe acute GVHD grades II-IV and III-IV for CD3+ and grades III-IV for CD34+ cell dose, respectively." (PMID 27036034, 2016). "As graft composition can be manipulated, e.g. by cryopreservation of a part of stem cell product, careful assessing the CD3+ and CD34+ graft content and tailoring the cell dose infused may help in reducing the risk of severe acute GVHD risk and improving transplantation outcome." (PMID 27036034, 2016). "A higher CD34+ cell dose was associated with inferior OS (P = 0.022) and increased NRM (P = 0.002), despite similar rates of graft failure and acute GVHD." (PMID 40773143, 2025). "Although they also observed a low incidence of acute GVHD in HCT from a graft with a higher dose of CD34+mono in humans, the study population was too small (n = 19) to conclude that it offered any clinical advantage." (PMID 31712609, 2019). "In the quartile of patients transplanted with the highest CD34+ graft content (>8.25 × 10^6 /kg) increased incidence of grade III-IV acute GVHD (18% vs. 7%, P = .02) was observed." (PMID 27036034, 2016). "Our results are in accordance with a single center Swedish study that reported the association between transplantation of high doses (≥17 x106 / kg) of CD34+ cells with higher incidence of acute GVHD grades II-IV." (PMID 27036034, 2016). "The incidence of acute GVHD was not significantly different between the groups (P = 0.478), suggesting no clear association between CD34+ cell dose and the development of clinically significant acute GVHD." (PMID 40773143, 2025). "Transfusions before transplantation, presence of HLA antibodies, composition of the graft (CD3+, CD19+, CD34+ cells), sibling or matched unrelated donor, female donor to male recipient, CMV serology and the development of acute GVHD (aGVHD), were considered potential risk factors." (PMID 31732859, 2020). "In vivo, adoptive therapy with CD34+ monocytes protected mice from acute GVHD." (PMID 32528476, 2020). "In conclusion, our results suggest that the incidence of severe acute GVHD post RIC allo-SCT, still a major cause of morbidity and mortality, is associated with the composition of the PBSC grafts, specifically it positively correlates with higher numbers of infused CD3+ and CD34+ cells." (PMID 27036034, 2016). "Twelve patients received delayed add-back of Tr1 cells after CD34-selected haploidentical HSCT: 7 died before day 100, the remaining 5 had accelerated immune reconstitution, but all had acute GVHD grade II–III." (PMID 31447852, 2019). "Interestingly, we did not observe an increase in acute GVHD with higher CD34+ cell doses, consistent with previous reports." (PMID 40773143, 2025). "In a multivariate analysis, CD3+ dose was the only adverse predicting factor for acute GVHD grade II-IV (HR= 2.1; 95%CI: 1.25-3.55, P = .005) and together with CD34+ dose for acute GVHD grade III-IV (CD3+, HR=3.6; 95%CI: 1.45-9.96, P = .006; CD34+, HR=2.65; 95%CI: 1.07-6.57, P = .04)." (PMID 27036034, 2016). "In humanized mice, purified human CD34+ cells, with almost no CD3+ cells, are transplanted into immunodeficient mice to create them, in order to prevent the development of acute GVHD." (PMID 34825089, 2021).
epithelioid sarcoma (12 papers, 2013 to 2025). An aggressive malignant neoplasm of uncertain differentiation, characterized by the presence of epithelioid cells forming nodular patterns. "Epithelioid sarcoma can show rhabdoid and spindle morphology with tumor necrosis, they generally express epithelial markers and CD34, and loss SMARCB1/INII1 expression and don’t express Myo-D1 and Myogenin." (PMID 36998041, 2023). "Epithelioid sarcoma is a malignant tumor affecting an older age group than MRT, with prominent rhabdoid cells and loss of nuclear INI1 in most cases, and it often shows CD34-positive staining, mainly located in the extremities." (PMID 29258531, 2017). "In our case, tumor cells were stained positive with CD31 and CD34 whereas they were negatively stained with panCK and EMA as the evidence of differentiation from carcinoma, epithelioid sarcoma, and epitheloid angiosarcoma." (PMID 34757619, 2023). "Both forms of epithelioid sarcoma typically coexpress CAM5.2, AE1/AE3, EMA, CK19, vimentin and are CD34 positive in 50 to 70% of cases." (PMID 31915021, 2020). "Second, immunohistochemistry shows that CD34 is expressed in more than 50% of epithelioid sarcomas, but a lack of CD34 expression is observed in SDUS." (PMID 37194064, 2023). "Both tumours show morphological and immunohistochemical overlap with coexpression of epithelial markers and vimentin; however epithelioid sarcomas express CD34, a marker which is typically absent in MRT." (PMID 25243090, 2014). "Tumour cells were negative for leukocyte common antigen (LCA), S-100, WT1, desmin, myogenin, neuron specific enolase (NSE), CD34, CK7, and TTF-1 excluding lymphoma, melanoma, Wilms' tumor, rhabdomyosarcoma, neuroblastoma, epithelioid sarcoma, and rhabdoid large cell carcinoma of lung, respectively." (PMID 25243090, 2014). "Furthermore, most epithelioid sarcomas are positive for CD34 and negative for ER, although there are rare cases of epithelioid sarcoma with myxoid degeneration, causing difficulty in identifying them from MELTVR." (PMID 39872225, 2025).
fibromatosis (12 papers, 2009 to 2025). A poorly circumscribed neoplasm arising from the soft tissues. "Inflammatory cell infiltration is not as diffuse as that in IMT; fibromatosis is also associated with CD34 positivity and catenin negativity and no expression of SMA or MSA." (PMID 36855132, 2023). "On IHC, fibromatosis cells typically display β-catenin nuclear staining and smooth muscle actin (SMA) cytoplasmic staining and lack immunoreactivity of CKs, p63, and CD34." (PMID 34322734, 2022). "Regarding to immunohistochemistry (IHC), positive results of Vimentin, β-catenin nuclear staining, and smooth muscle actin (SMA) cytoplasmic staining can be detected in fibromatosis cells whereas staining of S-100, CD34, CKs, and p63 are usually negative." (PMID 40008005, 2025). "Speaking of IHC, the result of staining of CKs, desmin, p63, CD34, and nuclear β-catenin on IHC are all negative while CK expression is rich in lesion of fibromatosis-like MBC and BDF." (PMID 40008005, 2025). "Low-grade fibromatosis-like metaplastic carcinoma tends to be negative for CD34 and strongly positive for cytokeratin, especially high molecular weight cytokeratins, and p63." (PMID 39526189, 2024). "In some series, fibromatosis did not stain for CD34 or S-100 protein, while CD34 staining and occasional S-100 protein positivity were seen in GIST." (PMID 19159438, 2009). "Another differential is a low-grade fibromatosis-like metaplastic carcinoma, which may be ruled out by negative CD34 immunostaining 19,20." (PMID 40093349, 2024). "CD34 may also be of value; it is often expressed by the stroma of PTs but is not seen in spindle cell metaplastic carcinoma or fibromatosis." (PMID 30567077, 2018). "CD34 is negative in fibromatosis-like MBC and fibromatosis but is typically positive in PASH, stroma-rich PT, myofibroblastoma, and solitary fibrous tumour." (PMID 34322734, 2022). "Fibromatosis (Fibr) served as a pathological negative control, and STAT6 and CD34 staining was absent in the respective tissue sample." (PMID 36428694, 2022).
keloid (12 papers, 2010 to 2025). An irregularly shaped, elevated mark on the skin caused by deposits of excessive amounts of collagen during wound healing. "Accumulative studies reported that the formation of the keloid was closely associated with the CD34−/α-SMA+/p16 + phenotype along with strong immunoreactivity for p16, abnormal signaling regulation pathways in the fibroblast such as noncoding RNA or exosome secretion." (PMID 36263010, 2022). "An epidermis of normal thickness and rete ridge formation with normal differentiation and proliferation could be seen, together with a CD34+/α-SMA−/p16− phenotype instead of the CD34−/α-SMA+/p16+ phenotype associated with keloid scars." (PMID 32528951, 2020). "Immunohistochemical analysis revealed robust CD34‐positive microvessels in Group 5 (23.1 ± 2.2 vessels/field), reflecting active angiogenesis akin to human keloids." (PMID 40488291, 2025). "Immunohistochemistry of keloids reveals the presence of CD34−/α-SMA+/p16+ cells, in contrast to CD34+/α-SMA-p16- cells in the dermis of normal adjacent skin." (PMID 39000244, 2024). "Rg3 decreased expression of CD34 in EPCs and decreased expression of CD31 and CD34 in cultured patient keloid samples, by 50 and 65%, respectively." (PMID 33113992, 2020). "Color ultrasound showed that there were hierarchical differences in the blood supply of the keloid, and further H&E, CD34, and eNOS staining showed that there were hierarchical differences in the spatial structure of blood vessels, fibroblasts, and collagen in the keloid." (PMID 39402198, 2025). "Furthermore, ex vivo explant cultures were used to test the effects of ADSC-conditioned medium (ADSC-CM) on CD31+ and CD34+ expression in keloid tissue." (PMID 29467010, 2018). "The transplantation success rate reached 80%, with nodules exhibiting dense collagen deposition (72.7% ± 3.8%), CD34‐positive microvessels (23.1 ± 2.2 vessels/field), and α‐SMA expression (11.29% ± 3.7%), closely mirroring human keloid histopathology." (PMID 40488291, 2025). "In our whole biopsy image analysis of keloid tissue, CD34 expression was found to be absent from the keloid dermis, but constitutively and abundantly present in normal skin and normotrophic scars." (PMID 32528951, 2020). "In addition, the keloid sections were incubated with antibodies against Phospho-Smad2/Smad3, Phospho-Erk1/2, CD31, CD34, collagen I, and collagen III at a dilution of 1:500." (PMID 27339758, 2016). "Hence, the increase rate of CD31+/ CD34+ implies that si-SPOCD1 and si- IFNγ + SPOCD1 can diminish the stemness of vascular endothelial cells, curtail the neovascularization within the vascular endothelium of keloid, thereby inhibiting the growth of keloid." (PMID 39820341, 2025). "Additionally, a thickened epidermis with involucrin overexpression and a CD34−/α-SMA+/p16+ dermal cell population could be found in both scar types, although α-SMA and p16 immunoreactivity were present in higher degrees in hypertrophic scars vs. keloids, respectively." (PMID 32528951, 2020).
malignant peripheral nerve sheath tumor (12 papers, 2014 to 2025). Malignant peripheral nerve sheath tumor (MPNST) is a rare and often aggressive soft tissue sarcoma occurring in a wide range of anatomical sites. "For rare uterine malignant peripheral nerve sheath tumors (MPNSTs), which may show focal positivity for S-100 and CD34, the key distinction lies in their usual expression of neural markers." (PMID 40936706, 2025). "However, in this study, CD34 exhibited strong positivity in 3 cases (3.0%), with one case identified as malignant schwannoma in the abdominal cavity and two cases located in the stomach." (PMID 39158355, 2024). "Approximately 1% of the tumor cells were S100+, CD34+, SOX10+, and MIB-1 positive, and the growth was diagnosed as a myxoid low-grade malignant peripheral nerve sheath tumor (MPNST)." (PMID 40777560, 2025). "Malignant peripheral nerve sheath tumors contain alternating hypocellular and hypercellular areas, focal HPC-like dispositions, CD34-positive reaction, and focal nerve sheath morphology." (PMID 41226013, 2025). "Malignant schwannomas show positive staining for vimentin and CD56 and negative staining for CK, LCA, CD34, SMA, desmin, chromogranin, and synaptophysin." (PMID 25276456, 2014).
myocardial ischemia (12 papers, 2011 to 2024). A disorder of cardiac function caused by insufficient blood flow to the muscle tissue of the heart. "Several clinical studies have shown the potential benefits of the transplantation of CD34+ cells for treating myocardial ischemia or other heart diseases, which is different from our study." (PMID 39198543, 2024). "Prior studies have claimed that CD34+ cells promote therapeutic angiogenesis through paracrine signaling in response to myocardial ischemia and have the potential to ensure engraftment of transplanted cells." (PMID 33211740, 2020). "Also, in our previous study, we demonstrated that transplantation of miR-377-silenced human CD34+ cells attenuated myocardial ischemia-reperfusion injury-induced interstitial fibrosis and left ventricular dysfunction in mice." (PMID 34485421, 2021). "Furthermore, CD34+ hematopoietic progenitors display pro-angiogenic capacities in animal models and in humans with acute myocardial ischemia." (PMID 21858032, 2011).
soft tissue sarcoma (12 papers, 2013 to 2025). A malignant neoplasm arising from muscle tissue, adipose tissue, blood vessels, fibrous tissue, or other supportive tissues excluding the bones. "Recognition of these findings is essential to avoid misdiagnosis with other CD34-positive perivascular neoplasms or myxoid soft tissue sarcomas." (PMID 41300877, 2025). "In that circumstance, RNA expression of TYR, CALD1 and CD34 has been shown to be discriminatory between spindloid oral melanoma and soft tissue sarcoma lesions [LOE 5, OEG D]." (PMID 38645640, 2024). "In conclusion, CD34 status was a useful prognostic factor for patients with soft tissue sarcomas diagnosed as MFSs and UPSs." (PMID 34326362, 2021). "While no solid tumors were detected, spleen enlargement and massive accumulation of green soft tissue resembling soft tissue sarcoma with increased vascularization at the trunk, abdomen, limbs, and kidneys were observed in CD34+ secondary engrafted NSG mice." (PMID 28985760, 2017). "SFTs are traditionally assimilated to soft tissue sarcomas and are often positive to CD34 staining." (PMID 40875449, 2025). "The positivity of CD4, CD8, and CD34 markers was associated with a low degree of aggressiveness of soft-tissue sarcomas, without invasion of the tumor margins, thus illustrating a better survival rate in these patients." (PMID 40362599, 2025). "CD4, CD8, and CD34 marker positivity was linked to soft-tissue sarcomas that were less aggressive and did not invade the tumor margins, indicating a higher survival percentage for these individuals." (PMID 40362599, 2025). "In conclusion, this study determined that relative RNA expression levels of TYR, CD34, and CALD1 discriminate between canine oral melanomas and soft tissue sarcomas." (PMID 34422947, 2021). "UPS can furthermore be differentiated from other soft-tissue sarcomas by negative staining for AE1/AE3, S-100, and CD34." (PMID 35747109, 2022).
type 1 diabetes (12 papers, 2013 to 2025). "IF was then performed on the pancreas sections derived from the rats of the control group and type 1 diabetes model group (150 mg/kg) to explore the relationship between CD34 and islet endocrine cells." (PMID 36467676, 2022). "An older age of type 1 diabetes diagnosis positively correlated with CD34+CD45dim cells (r = 0.361, p = 0.050)." (PMID 34267242, 2021). "Percentage of cells expressing CXCR7 at rest tended to be lower in the type 1 diabetes group, with CD34+CXCR7+ significantly so (p = 0.035)." (PMID 34267242, 2021). "However, percentage of CD34+CD45dimVEGFR2+ expressing CXCR4 was significantly higher in in the type 1 diabetes group (p = 0.050)." (PMID 34267242, 2021). "In treating type 1 diabetes mellitus (T1DM), intravenous administration of CD34+ bone marrow hematopoietic stem cells have shown the most promising results in restoring pancreatic function." (PMID 32765420, 2020). "They demonstrated that MSC and CD34+ HSC transplantation were the most successful and effective approaches in patients with insulin-dependent diabetes as they resulted in occurrence of insulin-free period in 20–60% of the patients and 7–50% reduction in their insulin requirement." (PMID 35501872, 2022). "There was a group x time interaction for the CD34+ HPCs, remaining elevated at 1 h post exercise in the type 1 diabetes group but not the healthy controls." (PMID 34267242, 2021). "Some clinical trials enrolled patients with early onset type I diabetes mellitus, who underwent the so called nonmyeloablative hematopoietic stem cell transplantation (AHST) of autologous CD34+ cells." (PMID 36611906, 2022). "CCN2 was found to be negative by PCR in mononuclear cells from 120 children (age 1.8–15.8 years) with insulin-dependent diabetes mellitus (IDDM) and CD34+ cells from 100 cord blood samples." (PMID 27485291, 2016).
acute coronary syndrome (11 papers, 2010 to 2023). Signs and symptoms related to acute ischemia of the myocardium secondary to coronary artery disease. "Circulating CD34+CD133+KDR+ EPCs levels in acute coronary syndromes with affective disorders was significantly lower than that in acute coronary syndromes without affective disorder." (PMID 34421539, 2021). "Activated platelets (P-selectin-positive platelets) express or release stromal cell-derived factor 1α (SDF-1α), leading to mobilization of bone marrow-derived CD34-positive cells into the peripheral blood in human acute coronary syndrome." (PMID 27374094, 2016). "Therefore, participants with a high level of CD34-positive cells should present with endothelial injury similar to participants with stable cardiovascular disease and acute coronary syndrome since endothelial repair activity should be stimulated by endothelial injury." (PMID 29165175, 2017).
AIDS (11 papers, 2006 to 2025). A syndrome resulting from the acquired deficiency of cellular immunity caused by the human immunodeficiency virus (HIV). "Absolute cell counts have been shown to be a major tool for laboratory diagnosis for a variety of pathological conditions, including CD4+ T-cells for Acquired ImmunoDeficiency Syndrome and haematopoietic progenitor cells expressing CD34 for cord blood transplants and autotransplantation." (PMID 30240448, 2018). "(i) The first theme was to define humanized mice to the audience as immunodeficient mice transplanted with human cells and/or tissues and to briefly overview how to generate two common humanized mouse models for HIV/AIDS research – human CD34 transplant mice and bone marrow/liver thymus (BLT) mice." (PMID 41221300, 2025). "Our data suggest that the anti-HIV-1 integrase scaffold is a promising antiviral molecule that could be applied to human CD34+ HSPC-based gene therapy for AIDS patients." (PMID 35216446, 2022). "To date, the RNAi-based agents that have reached clinical testing for HIV/AIDS have relied on ex vivo delivery of lentiviral vectors into specific cell types, such as CD4+ T cells or CD34+ HPCs, which are then transfused back into the patient." (PMID 26019725, 2015). "All the results suggest that ablation of CCR5 via the CRISPR/SaCas9 system may be a safe alternative approach for generation of HIV-1 resistance in human CD4+ T cells and CD34+ HSPCs, however, there are also potential drawbacks in targeting CCR5 alone in HIV-1/AIDS gene therapy." (PMID 31186067, 2019).